ARHGAP10 (Rho GTPase activating protein 10)
Description:
GTPase-activating protein that catalyzes the conversion of active GTP-bound Rho GTPases to their inactive GDP-bound form, thus suppressing various Rho GTPase-mediated cellular processes. Also converts Cdc42 to an inactive GDP-bound state. Essential for PTKB2 regulation of cytoskeletal organization via Rho family GTPases. Inhibits PAK2 proteolytic fragment PAK-2p34 kinase activity and changes its localization from the nucleus to the perinuclear region. Stabilizes PAK-2p34 thereby increasing stimulation of cell death (By similarity). Associates with MICAL1 on the endosomal membrane to promote Rab8-Rab10-dependent tubule extension. After dissociation with MICAL1, recruits WDR44 which connects the endoplasmic reticulum (ER) with the endosomal tubule, thereby participating in the export of a subset of neosynthesized proteins.
Synonyms: GRAF2; FLJ20896; FLJ41791; PS-GAP; PSGAP
Tractability: Antibody: UniProt places it where antibodies can reach, with high confidence; its Gene Ontology location is reachable by antibodies, with medium confidence. PROTAC: ubiquitination databases record sites on it; its protein half-life has been measured.
Gene: Protein-coding gene on chromosome 4 (147,731,922 to 148,072,780, forward strand). Ensembl gene ENSG00000071205.
Subcellular location: Cytoplasm; Cytoplasm, perinuclear region; Cell membrane; Endosome membrane
Subcellular location (Human Protein Atlas): Nucleoplasm; Cytosol; Nuclear membrane
Pathways (Reactome):
Signal Transduction: CDC42 GTPase cycle; RAC1 GTPase cycle; RHOA GTPase cycle
Programmed Cell Death: Regulation of PAK-2p34 activity by PS-GAP/RHG10
Gene Ontology:
Molecular function: protein binding; GTPase activator activity
Biological process: cytoskeleton organization; negative regulation of apoptotic process; regulation of small GTPase mediated signal transduction; signal transduction
Cellular component: cytosol; endosome membrane; cytoplasm; perinuclear region of cytoplasm; plasma membrane
Genetic constraint (gnomAD): Loss-of-function variants: 68 observed, 93.03 expected, observed/expected ratio (o/e) 0.73, 90% interval 0.6 to 0.89. The upper end of that interval is the gene's LOEUF score, 0.89, which puts it in group 3 of 6, group 1 being the genes least tolerant of losing a copy. Missense variants: 894 observed, 932.85 expected, observed/expected ratio (o/e) 0.96, 90% interval 0.91 to 1.01. Synonymous variants: 335 observed, 339.47 expected, observed/expected ratio (o/e) 0.99, 90% interval 0.9 to 1.08.
Homologues: Orthologues: chimpanzee ARHGAP10 (99% identical), macaque ARHGAP10 (98% identical), dog ARHGAP10 (94% identical), pig ARHGAP10 (92% identical), mouse Arhgap10 (91% identical), rat Arhgap10 (91% identical), guinea pig ARHGAP10 (88% identical), rabbit ARHGAP10 (84% identical), tropical clawed frog arhgap10 (72% identical), zebrafish arhgap10 (60% identical), Drosophila melanogaster Graf (41% identical), Caenorhabditis elegans T04C9.1 (38% identical). Paralogues in human: ARHGAP26 (57% identical), ARHGAP42 (55% identical), OPHN1 (44% identical).
Diseases named in the same sentence as ARHGAP10 in open-access papers:
ARHGAP10 is named in the same sentence as 56 diseases in open-access papers, as found by Europe PMC text mining. Sharing a sentence is not in itself a finding about the gene and the disease. The quoted sentences say what the papers report.
ovarian carcinoma (9 papers, 2016 to 2024). A malignant neoplasm originating from the surface ovarian epithelium. "ARHGAP10 is a tumor‐suppressor gene related to ovarian cancer (OC) progression; however, its specific mechanism is unclear." (PMID 38230565, 2024). "ARHGAP10 is well known as a tumor suppressor and has been demonstrated in a variety of cancers, such as Uterine leiomyomas (ULs), prostate cancer, ovarian cancer (OC), lung cancer, colon carcinoma (CRC) and BC." (PMID 38041020, 2023). "ARHGAP10 has also been consolidated as a tumor-suppressor in ovarian cancer cells by inhibiting cell cycle progression and inducing apoptosis resulting in suppression of tumorigenesis." (PMID 34493786, 2021). "CXCL12/CXCR4 promotes invasion of ovarian cancer cells by suppressing ARHGAP10 expression via the VEGF/VEGFR2 signaling pathway." (PMID 34907282, 2021). "Our data demonstrated that ARHGAP10 expression was downregulated in ovarian cancer tissues, which was correlated with poor survival of patients with ovarian cancer." (PMID 27010858, 2016). "The effects of ARHGAP10 overexpression in the proliferation, adhesion, migration and invasion of ovarian cancer cells were then assessed." (PMID 27010858, 2016). "To validate the GSEA results, we then detected the expression of cell cycle (PCNA and PLK1), DNA replication (MCM2 and MCM3) and BER pathways-related proteins (PARP1 and PARP2) in ovarian cancer cells transiently overexpressed ARHGAP10." (PMID 27010858, 2016). "ARHGAP10 expression was then estimated in five ovarian cancer cell lines, OVCAR3, A2780, CAOV3, SKOV3 and HO-8910, by western blotting." (PMID 27010858, 2016). "In the present study, we compared ARHGAP10 expression between ovarian cancer and paired normal tissues." (PMID 27010858, 2016). "Ectopic expression of ARHGAP10 in two ovarian cancer cell lines resulted in a significant inhibition in cell proliferation, adhesion, migration and invasion, and a remarkable induction in cell cycle G1 phase arrest and apoptosis." (PMID 27010858, 2016). "Then, according to the relative ARHGAP10 expression in tumor tissues, the 75 ovarian cancer patients were classified into two groups: relative high group (n=37) and relative low group (n=38) by using a value of 1.16 (median) as a cutoff." (PMID 27010858, 2016). "Ectopic expression of ARHGAP10 in two ovarian cancer cell lines with lower expression of ARHGAP10 (A2780 and HO-8910) dramatically suppressed cell proliferation in vitro." (PMID 27010858, 2016). "In conclusion, our study suggests that ARHGAP10 acts as a tumor suppressor in ovarian cancer cell line, and the downregulation of ARHGAP10 expression is closely associated with the poor prognosis of ovarian cancer." (PMID 27010858, 2016). "To further investigate the functions of ARHGAP10 in ovarian cancer, we explored the effects of ARHGAP10 overexpression on the cell behavior of ovarian cancer cells." (PMID 27010858, 2016). "Luo pointed out that ARHGAP10 may serve as a tumor inhibitor through suppressing adhesion, migration, and invasion of the ovarian cancer cells." (PMID 35769708, 2022). "Downregulated ARHGAP10 inhibits tumorigenicity of ovarian cancer cells." (PMID 34131588, 2021). "ARHGAP10 acts as tumor suppressor in ovarian cancer, lung cancer and gastric cancer." (PMID 31396458, 2019). "Base excision repair is enriched for ARHGAP10 in ovarian cancer." (PMID 31396458, 2019). "Whether ARHGAP10 can be used as a potential therapeutic target for ovarian cancer remains to be further investigated." (PMID 27010858, 2016). "Furthermore, overall survival in ovarian cancer patients with higher expression of ARHGAP10 was longer than those with lower expression." (PMID 27010858, 2016). "ARHGAP10 expression was decreased in 77.3% (58/75) of tested ovarian cancer tissues." (PMID 27010858, 2016). "Then we assessed whether ARHGAP10 affects the cell cycle of ovarian cancer cells by propidium iodide (PI) staining and flow cytometry analysis." (PMID 27010858, 2016).
ovarian carcinoma (continued). "Gene set enrichment analysis on The Cancer Genome Atlas dataset showed that KEGG cell cycle, replication and base excision repair (BER) pathways were correlatively with the ARHGAP10 expression, which was further confirmed in ovarian cancer cells by western blotting." (PMID 27010858, 2016). "Here, we aimed to evaluate ARHGAP10 expression profile and functions in ovarian cancer." (PMID 27010858, 2016). "Our study provides the evidences that ARHGAP10 expression is decreased in ovarian cancer, and it may be a prognosis factor and tumor suppressor for this disease." (PMID 27010858, 2016). "Our data indicate that ARHGAP10 may act as a tumor suppressor in ovarian cancer." (PMID 27010858, 2016). "We then detected mRNA levels of ARHGAP10 in 75 pairs of ovarian cancer and adjacent non-tumorous epithelial tissues by quantitative real-time PCR." (PMID 27010858, 2016). "Statistical analysis with student's t-test suggested that ARHGAP10 expression was significantly downregulated in ovarian cancer tissues compared with that in noncancerous tissues (P<0.0001)." (PMID 27010858, 2016). "The decreased expression of ARHGAP10 was found in 77.3% (58/75) of ovarian cancer tissues, compared with their non-tumorous counterparts." (PMID 27010858, 2016).
schizophrenia (7 papers, 2020 to 2024). A major psychotic disorder characterized by abnormalities in the perception or expression of reality. "Examples include dysregulation of Rho GTPase, e.g., ARHGAP10, a gene for schizophrenia risk, encoding Rho GTPase-activating protein 10, which also plays a role in the proliferation, migration, and invasion of lung cancer cells, and prostate cancer." (PMID 37124926, 2023). "Arhgap10 S490P/NHEJ mice carry double variants of the Arhgap10 gene that mimic the ARHGAP10 variations discovered in a Japanese patient with schizophrenia (case #5)." (PMID 37958606, 2023). "Mouse models have been developed based on schizophrenia-associated genetic variants involved in small GTPase RhoA signaling, including variants affecting the Arhgap10, Kalrn, and Rtn4r genes, and their phenotypic characterization has been performed." (PMID 37958606, 2023). "Mutations in the ARHGAP10 gene have been linked to cognitive and psychiatric symptoms and schizophrenia." (PMID 35624318, 2022). "In conclusion, our results suggested that Arhgap10 gene mutations have a pathophysiologic and pathogenic role, involving structural and functional changes in the MSNs of striatum and NAc, in schizophrenia." (PMID 33482876, 2021). "We recently found a significant association between schizophrenia and exonic CNVs in the Rho GTPase activating protein 10 (Arhgap10) gene." (PMID 33482876, 2021). "The schizophrenia patient (Case #5) who has both an exonic deletion and a missense variant (p.S490P) in Arhgap10 showed visual hallucination and cognitive impairment." (PMID 33482876, 2021). "CNVs in ARHGAP10 were identified in seven patients with schizophrenia (six with deletions and one with duplication) but not in controls, and there was a significant association of ARHGAP10 CNVs with schizophrenia in Japanese patients (OR = 12.3, p = 0.015)." (PMID 37958606, 2023). "Collectively, these results suggest that schizophrenia-associated Arhgap10 gene variants result in morphological abnormalities of neurons in the mPFC, and these abnormalities are associated with vulnerability to cognitive deficits induced by methamphetamine treatment." (PMID 37958606, 2023). "Recently, a significant association between schizophrenia and exonic copy-number variations in the ARHGAP10 gene in Japanese patients has been reported, constituting for the first time a link between ARHGAP10 and neurological disease." (PMID 35624318, 2022). "Targeting the regulation of Rho GTPase and the downstream signaling may provide new therapeutic approaches for the treatment of schizophrenia patients with Arhgap10 gene mutations." (PMID 33482876, 2021). "Taken together, these results suggested that schizophrenia-associated Arhgap10 gene mutations result in morphological abnormality of neurons in the striatum and NAc, which may be associated with vulnerability of cognition to methamphetamine treatment." (PMID 33482876, 2021). "In particular, rare ARHGAP10 variants are genetically and biologically associated with schizophrenia, and Rho-kinase may represent a promising drug target for schizophrenia treatment in patients with variants of ARHGAP10 and possibly other genes related to the RhoA/Rho-kinase pathway." (PMID 37958606, 2023). "In particular, Rho-kinase inhibitors exhibited anti-psychotic-like effects not only in Arhgap10 S490P/NHEJ mice but also in pharmacologic models of schizophrenia (methamphetamine- and MK-801-treated mice)." (PMID 37958606, 2023). "Arhgap10 S490P/NHEJ mice are a unique genetic mouse model of schizophrenia with constructive, phenotypic, and predictive validity." (PMID 37958606, 2023). "We recently found a significant association between exonic copy-number variations in the Rho GTPase activating protein 10 (Arhgap10) gene and schizophrenia in Japanese patients." (PMID 33482876, 2021).
schizophrenia (continued). "Previous studies indicated the morphological abnormality of pyramidal neurons in the frontal cortex of patients with schizophrenia, whereas ARHGAP10 is reported to regulate cellular morphology through the RhoA and Cdc42 pathways in fibroblasts." (PMID 33482876, 2021). "Recently, several variants of RhoA-associated GAPs, including ARHGAP10, ARHGAP18, and p250GAP, and GEFs such as KALRN and ARHGEF11, were reported to be significantly associated with the development of schizophrenia." (PMID 37958606, 2023). "In terms of drug development, it is important to assess whether Rho-kinase inhibitors exhibit antipsychotic effects in patients with schizophrenia who carry no variants in ARHGAP10 or related genes." (PMID 37958606, 2023). "In particular, Rho-kinase inhibitors exhibit anti-psychotic-like effects not only in Arhgap10 S490P/NHEJ mice, but also in pharmacologic models of schizophrenia (methamphetamine- and MK-801-treated mice)." (PMID 37958606, 2023). "The relative expression levels of ARHGAP10 mRNA in lymphoblastoid cell lines established from the peripheral blood of patients with exonic ARHGAP10 CNVs were significantly decreased compared to those in patients with schizophrenia without ARHGAP10 CNVs and in a control group." (PMID 37958606, 2023).
lung cancer (6 papers, 2019 to 2024). A malignant neoplasm involving the lung. "In non‐small cell lung cancer, emerging evidence has indicated that the antitumor mechanism of ARHGAP10 directly mediated the epithelial‐mesenchymal transition process via the PI3K/Akt/GSK3β pathway." (PMID 38230565, 2024). "Circular RNA Rho GTPase‐activating protein 10 (circ‐ARHGAP10) is formed by the exon of the ARHGAP10 gene through circularization and promotes proliferation, migration, invasion, and glycolysis of non‐small cell lung cancer cells." (PMID 38230565, 2024). "However, the correlation of ARHGAP10 expression with EMT of lung cancer cells is unclear and remains to be elucidated." (PMID 34174897, 2021). "However, the correlation of ARHGAP10 expression with epithelial–mesenchymal transition (EMT) in lung cancer cells is unclear and remains to be elucidated." (PMID 34174897, 2021). "Metastasis and the Wnt signaling pathway are regulated by ARHGAP10 in lung cancer cells." (PMID 31396458, 2019). "In present research, ARHGAP10 can decrease the expression levels of constituents of PI3K/Akt/GSK3β pathway and subsequently downregulated EMT biomarkers expression in lung cancer." (PMID 34174897, 2021). "The positive mode has marker traits pulmonary function and the C-reactive protein, and the few markers genes (IL6R, ARHGAP10, BCL7B, PABPC4) are also involved in immune response and lung cancer progression." (PMID 34157017, 2021). "Emerging evidence has indicated that ARHGAP10 inhibited proliferation and migration of lung cancer, but the biological process and potential mechanism of ARHGAP10 in NSCLC epithelial–mesenchymal transition has not been previously verified." (PMID 34174897, 2021).
prostate carcinoma (5 papers, 2016 to 2023). A carcinoma that arises from epithelial cells of the prostate gland. "However, in prostate cancer, Hua Gong claimed that a high expression of ARHGAP10 correlates with poor prognosis, which supports our result." (PMID 35769708, 2022). "ARHGAP10 has been reported to be downregulated in prostate cancer and may serve as a candidate tumor suppressor." (PMID 34174897, 2021).
breast carcinoma (4 papers, 2019 to 2022). "To clarify the mechanisms underlying ARHGAP10 downregulation in breast cancer, we analyzed the region 2000bp upstream of ARHGAP10, and showed the presence of CpG islands in this region." (PMID 31396458, 2019). "Further investigations of the mechanisms underlying the downregulation of ARHGAP10 in breast cancer and other cancers are needed." (PMID 31396458, 2019). "Here, we showed that ARHGAP10 expression was downregulated at both the transcriptional and protein levels in breast cancer." (PMID 31396458, 2019). "The expression trend of ARHGAP10 in breast cancer cell lines was roughly consistent with that in the clinical tissue samples." (PMID 31396458, 2019). "The targets of ARHGAP10, i.e., GTPases, play a role in cytoskeleton formation and proliferation and are involved in migration and invasion of breast cancer cells." (PMID 31396458, 2019). "We confirmed that ARHGAP10 was significantly downregulated in breast cancer, and low expression of ARHGAP10 was related to a high Ki-67 index, advanced cTNM stage and low RFS rate." (PMID 31396458, 2019). "Correlation between the clinicopathological parameters and the expression of ARHGAP10 in 190 breast cancer cases." (PMID 31396458, 2019). "A total of 1,097 breast cancer samples were divided into two groups by the median expression of ARHGAP10, namely ARHGAP10-low group and ARHGAP10-high group." (PMID 31396458, 2019). "In summary, the expression of ARHGAP10 is downregulated in breast cancer, and relative low expression of ARHGAP10 is correlated with malignant characteristics such as a high Ki-67 index, advanced cTNM stage, poor response to chemotherapy and low RFS rates." (PMID 31396458, 2019). "It would therefore be of value to investigate how ARHGAP10 is involved in these signaling pathways to play its biological roles in breast cancer." (PMID 31396458, 2019). "The present study was intended to investigate the expression pattern and potential biological function of ARHGAP10 in breast cancer." (PMID 31396458, 2019). "ARHGAP10 protein expression was examined by immunohistochemistry (IHC) in 190 breast cancer and 30 corresponding adjacent normal breast tissue samples." (PMID 31396458, 2019). "RT-qPCR analysis of 30 paired breast cancer and corresponding adjacent normal tissues was performed to confirm the expression pattern of ARHGAP10 in breast cancer." (PMID 31396458, 2019). "ARHGAP10 was not only downregulated in breast cancer but also in other cancers including bladder cancer, esophageal cancer, liver cancer, prostate adenocarcinoma, rectum adenocarcinoma, skin cutaneous melanoma, uterine carcinosarcoma according to GEPIA." (PMID 31396458, 2019). "ARHGAP10 mRNA and protein expression was lower in breast cancer tissues than in adjacent normal tissues." (PMID 31396458, 2019). "We analyzed 190 breast cancer tissue samples and 30 adjacent normal tissues, and the results showed that ARHGAP10 was downregulated in breast cancer tissues and low expression was correlated with high Ki-67 index and advanced cTNM stage." (PMID 31396458, 2019). "Downregulating the expression of ARHGAP10 could lead to a more advanced stage and a higher Ki-67 index in breast cancer." (PMID 35769708, 2022). "ARHGAP10, a member of GAPs, is downregulated in ovarian and breast cancer." (PMID 34733886, 2021). "This suggested that ARHGAP10 played a role in metastasis and proliferation in breast cancer." (PMID 31396458, 2019). "Additional studies are required to gain more insights into the role of ARHGAP10 in breast cancer." (PMID 31396458, 2019). "ARHGAP10 is involved in cancer-related signaling pathways in breast cancer." (PMID 31396458, 2019). "Additionally, we conducted GSEA to identify the possible biological functions and potential signaling pathways related to ARHGAP10 in breast cancer." (PMID 31396458, 2019). "Little is elucidated about ARHGAP10 in breast cancer before." (PMID 31396458, 2019).